ZNF281 (zinc finger protein 281)
Diseases named in the same sentence as ZNF281 in open-access papers (continued):
Sharing a sentence is not in itself a finding about the gene and the disease.
leiomyosarcoma (2 papers, 2020 to 2022). An uncommon, aggressive malignant smooth muscle neoplasm, usually occurring in post-menopausal women. "Contrary to what happens in skeletal and smooth muscle tissues, the expression of ZNF281/Zfp281 is significantly elevated in rhabdomyosarcoma and leiomyosarcoma tumors." (PMID 31782884, 2020). "In addition, we found that in rhabdomyosarcoma and leiomyosarcoma tumors, the expression of ZNF281/Zfp281 is significantly higher compared with normal counterparts." (PMID 31782884, 2020).
non-small cell lung carcinoma (2 papers, 2021 to 2023). A group of at least three distinct histological types of lung cancer, including non-small cell squamous cell carcinoma, adenocarcinoma, and large cell carcinoma. "A recent study showed that inhibiting ZNF281 leads to potent radiosensitization of non-small cell lung cancer." (PMID 37939252, 2023).
oral squamous cell carcinoma (2 papers, 2021 to 2023). "This is the first description of ZNF-281 gene expression in oral squamous cell carcinoma." (PMID 34071380, 2021). "However, while reviewing the literature, there has been no mention of ZNF-281’s activity in oral squamous cell carcinoma (OSCC)." (PMID 34071380, 2021).
osteosarcoma (2 papers, 2021 to 2023). A usually aggressive malignant bone-forming mesenchymal neoplasm, predominantly affecting adolescents and young adults. "Among the known lncRNAs, lncRNA zinc finger protein 281 (lnc-ZNF281) is characterized as a tumor suppressor in osteosarcoma by downregulating the expression of miR-144." (PMID 34056009, 2021).
pancreatic adenocarcinoma (2 papers, 2022 to 2024). "Then, in three types of cancer, cervical squamous cell carcinoma and endocervical adenocarcinoma (CESC), pancreatic adenocarcinoma (PAAD), and stomach adenocarcinoma (STAD), ZNF281 was confirmed as a good prognostic molecular marker considering the high accuracy in the clinical diagnostic feature." (PMID 36685971, 2022). "We further investigated the role of ZNF281 in cervical squamous cell carcinoma and endocervical adenocarcinoma (CESC), pancreatic adenocarcinoma (PAAD), and stomach adenocarcinoma (STAD) and confirmed the high accuracy in the clinical diagnostic feature." (PMID 36685971, 2022).
alcoholic liver diseases (1 paper, 2023). A disorder caused by damage to the liver parenchyma due to alcohol consumption. "In summary, the results above suggested that ZNF281 deficiency relieves liver injury and hepatocyte senescence in mice with alcoholic liver disease." (PMID 36514923, 2023). "In this work, we used both in vivo and in vitro models to mimic clinical alcoholic liver disease to study the pathogenic role of ZNF281 and potential mechanisms." (PMID 36514923, 2023). "In summary, our study for the first time reveals the pathogenic role of ZNF281 in alcoholic liver disease and elucidates a potential molecular mechanism, which may provide a novel insight into the pathophysiological researches of alcoholic liver disease." (PMID 36514923, 2023). "According to the aggressive role of ZNF281 in causing ethanol‐induced hepatocyte senescence and cytotoxicity, we further determined whether ZNF281 deficiency could provide hepatoprotection against alcoholic liver disease in vivo." (PMID 36514923, 2023). "In this study, the implication of ZNF281 was extended by discussing its role in alcoholic liver disease and our results suggested that high ZNF281 expression under ethanol exposure was a critical inducer of hepatocyte senescence and alcoholic liver injury." (PMID 36514923, 2023). "This study provides a novel factor ZNF281 as a driver of hepatocyte senescence during alcoholic liver disease." (PMID 36514923, 2023). "Based on the model, this study showed that both mRNA and protein abundance of ZNF281 in murine liver tissues were progressively increased during alcoholic liver disease." (PMID 36514923, 2023). "Collectively, these data indicated that ZNF281 expression positively correlates with the progress of alcoholic liver disease." (PMID 36514923, 2023). "HK2 protein abundance in liver tissues was reduced in mice with alcoholic liver disease, which was rescued by ZNF281 knockdown." (PMID 36514923, 2023). "Targeting at modulating ZNF281 could be anticipated to be a potential therapeutic strategy for alcoholic liver disease." (PMID 36514923, 2023).
breast tumors (1 paper, 2022). "Furthermore, ZNF281 was highly expressed in BC and was more highly expressed in metastatic breast tumors than in those without metastasis." (PMID 36438499, 2022).
cervical cancer (1 paper, 2024). A primary or metastatic malignant neoplasm involving the cervix. "Although the zinc finger transcription factor 281 (ZNF281)/ZBP-99 protein has been shown to promote tumor progression, its role in the development of cervical cancer remains unclear." (PMID 39518154, 2024). "Besides the ZNF281 protein, long non-coding RNA (lncRNA) ZNF281 was also reported to be involved in the malignant progression of various malignant disorders, including cervical carcinoma, by targeting Kruppel-like factor 15 (KLF15)." (PMID 39518154, 2024). "Additionally, ZNF281 was expressed in human cervical carcinoma cell lines, including HeLa, SiHa, C-33 A, CaSki, and HT-3, and is localized in both the cell nucleus and cytoplasm." (PMID 39518154, 2024).
Cirrhosis (1 paper, 2023). A chronic disorder of the liver in which liver tissue becomes scarred and is partially replaced by regenerative nodules and fibrotic tissue resulting in loss of liver function. "Analyses of expression data in GSE14323 showed increased expression of ZNF281 in HCC compared with normal and cirrhosis liver tissues but decreased expression of PGC-1α, TFAM, TFB1M, and TFB2M." (PMID 37880213, 2023).
colorectal tumor (1 paper, 2024). "High expression of ZNF281 after surgical resection of a colorectal tumor correlates with a higher recurrence rate 3 years later." (PMID 39518154, 2024).
corneal diseases (1 paper, 2024). "To further explore the role of ZNF281 and FOXO3, we analyzed their expression changes in other corneal diseases." (PMID 39254179, 2024).
Ewing sarcoma (1 paper, 2020). A small round cell tumor that lacks morphologic, immunohistochemical, and electron microscopic evidence of neuroectodermal differentiation. "In line with this, high expression of ZNF281 is associated with a significantly worse prognosis in Ewing’s sarcoma." (PMID 31782884, 2020). "The Kaplan–Meier survival probability analysis in Ewing’s sarcoma performed by subdividing patients in high‐ and low‐expressing ZNF281 highlighted a significantly worse prognosis in high expressors (log‐rank P = 0.032)." (PMID 31782884, 2020).
keratoconus (1 paper, 2024). A degenerative, structural disorder of the eye, characterized by a cone-shaped protrusion of the cornea. "We investigated the role of ZNF281 and FOXO3 using single‐cell transcriptomic datasets from human keratoconus corneas, a disease characterized by decreased antioxidant capacity." (PMID 39254179, 2024). "We found downregulation of ZNF281 and FOXO3, along with most of their targeted antioxidant genes in keratoconus corneas, suggesting that the dysregulation of the antioxidant programs mediated by ZNF281 and FOXO3 may be involved in the development of keratoconus." (PMID 39254179, 2024).
liver disease (1 paper, 2023). "In HCC, ZNF281 was found be to aberrantly upregulated and promoted HCC invasion and migration, which was a preliminary reflection of the potential correlation between ZNF281 and liver disease." (PMID 36514923, 2023).
myelogenous leukemia (1 paper, 2022). "We recently reported similar GC-rich DNA consensus motifs, unique and overlapping chromatin occupancy sites for ZNF148 and ZNF281, and their functional redundancy in myelogenous leukemia cells." (PMID 36207293, 2022).
neuroendocrine tumors (1 paper, 2022). "The opposite impact of TF score on the survival of NEL and NBL may attributed to BATF3, GMEB1 and REST, since NFIA and ZNF281 showed uniform influence on the survival of the two neuroendocrine tumors." (PMID 36713370, 2022).
osteoporosis (1 paper, 2020). A condition of reduced bone mass, with decreased cortical thickness and a decrease in the number and size of the trabeculae of cancellous bone (but normal chemical composition), resulting in increased fracture incidence. "Zinc finger protein 281 (ZNF281), involved in bone metabolism, is related to osteoporosis and osteosarcoma." (PMID 32788627, 2020).
ovarian carcinoma (1 paper, 2019). A malignant neoplasm originating from the surface ovarian epithelium. "The aim of this study was to analyze the expressions of ZNF143 and ZNF281 in tumor tissues and to verify if they correlate with clinicopathological characteristics of borderline ovarian tumors and low-grade ovarian cancers." (PMID 30885238, 2019). "The expression patterns of ZNF143 and ZNF281 identified in this study suggest that both sBOTs and low-grade ovarian cancers might undergo a dynamic epithelial-mesenchymal interconversion." (PMID 30885238, 2019).
ovarian tumors (1 paper, 2019). "However, still little is known about the role of ZNF143 and ZNF281 in the pathogenesis of ovarian neoplasms, and published evidence in this matter is sparse and inconclusive." (PMID 30885238, 2019). "Moreover, we compared the expressions of ZNF143 and ZNF281 in these two groups of ovarian tumors." (PMID 30885238, 2019). "The proportions of the ovarian tumors that tested positively for ZNF143 and ZNF281 were 90 and 57%, respectively." (PMID 30885238, 2019). "Nevertheless, it should be emphasized that the majority of ovarian tumors included in this study tested positively for ZNF143 and ZNF281." (PMID 30885238, 2019).
rectal cancer (1 paper, 2023). A primary or metastatic malignant neoplasm that affects the rectum. "The high expression of ZNF281 may predict poor tumour response and prognosis in rectal cancer patients receiving NART, encouraging us to explore further the status of the expression and clinical relevance of ZNF281 in rectal carcinoma." (PMID 37939252, 2023).
cancer (24 papers, 2017 to 2025). A tumor composed of atypical neoplastic, often pleomorphic cells that invade other tissues. "Other interesting genes were PRDM9 and ZNF281, both of which play a role in DNA repair and have been shown to be responsible for frequent mutations in cancer." (PMID 34900699, 2021). "Based on our data, we suppose that DNA repair deficiency (because of a low level of ZNF-281) dominates over others and leads to cancer development in OSCC." (PMID 34071380, 2021). "DNA damage, induced by drugs, has caused an increase in ZNF-281 expression in cell lines from diversified cancers." (PMID 34071380, 2021). "Although the known functions of ZNF281 in cancer biology have been limited, recent studies have provided new insights into the function of ZNF281 in EMT and its association with the WNT signaling pathway." (PMID 29312619, 2017). "ZNF281 has been widely reported to be associated with the progression of many cancers." (PMID 36514923, 2023). "Zinc-finger-281’s (ZNF-281’s) influence on carcinogenesis, progression and metastasis (through epithelial–mesenchymal transition induction) and its association with poor prognosis have been reported in many cancers." (PMID 34071380, 2021). "This could be associated with the fact that ZNF-281 has an impact on different mechanisms with opposite effects on cancer progression such as metastasis and DNA repair." (PMID 34071380, 2021). "Taken altogether, this evidence suggests that ZNF281 may contribute to the loss of cell-cell contacts and determine mesenchymal phenotype of cancer cells." (PMID 30885238, 2019). "Indeed, bioinformatic analysis of cancer patients treated with genotoxic therapies demonstrates that low expression of ZNF281 is associated with better prognosis, while patients with elevated levels of ZNF281 have a decreased survival probability." (PMID 31570788, 2020). "We explored differences in ZNF281 expression in Pan-cancer and normal tissues, the effect of its expression on prognosis of patients treated with 5-fluorouracil (5-FU)." (PMID 38880820, 2024). "Transwell assays were used to observe the effect of ZNF281 in the migration and invasion of cancer cells." (PMID 39518154, 2024). "ZNF281 was firstly identified as an EMT driver in cancer, which prompted us to explore the functional relevance between mitochondrial biogenesis and EMT, invasion, and metastasis, in HCC." (PMID 37880213, 2023). "ZNF281 showed higher expression in cancer tissues than in para-cancerous tissues while ATP5B showed the opposite pattern, supporting previous reports." (PMID 37880213, 2023). "ZNF281 is a zinc‐finger factor that is aberrantly expressed in various types of cancers and leads to cancer progression and metastasis." (PMID 36514923, 2023). "Considering the heterogeneity and complexity of tumors, we analyzed the ZNF281 expression in pan-cancer and related normal tissues using RNA-seq data from TCGA and GTEx and found the upregulation of ZNF281 in most types of cancer." (PMID 36685971, 2022). "Beyond that, based on these three types of cancers, we analyzed the ZNF281-related tumor immune infiltration and DNA methylation sites and finally built risk prediction models for future disease diagnosis." (PMID 36685971, 2022). "Further work addressing both ZNF148 and ZNF281 within the same cellular context will be required to better understand the regulatory mechanisms contributing to the cancer stem cell state and metastatic progression." (PMID 36207293, 2022). "Following that, we found that ZNF281 (the human homolog of Zfp281) was upregulated in most types of cancer and related to worse prognosis in 10 tumors." (PMID 36685971, 2022). "With bioinformatics prediction tools (TargetScan, miRDB and Starbase), ZNF281, a carcinogene in cancers, was found to be a target of miR‐488." (PMID 33320427, 2022). "More importantly, high ZNF281 expression in cancer tissues enhances metastatic potential and reduces patient survival." (PMID 33320427, 2022).
cancer (continued). "Taken together, these results, identifying ZNF281 as a controller of relevant and strategic biological processes, underline that a dysregulation in the expression and function of the protein can be preparatory to the onset of a pathological condition, whether of a fibrotic or cancer nature." (PMID 36142169, 2022). "The majority of cancer studies emphasized that ZNF-281 gene up-regulation correlates with cancer presence, progression, metastasis and poor prognosis." (PMID 34071380, 2021). "ZNF-281 expression is regulated by various cancer type-related miRNA expressions, phosphorylation and acetylation, which depends on the specific tissue’s microenvironment." (PMID 34071380, 2021). "We know that the NF-κB1 pathway has an essential role in cancer invasion; therefore, we strongly recommend focusing on this molecular pathway and its interactions with ZNF-281 in OSCC." (PMID 34071380, 2021). "It is worth mentioning that transcription of ZNF-281 is controlled by SOX4—an agent presented in many cancers and responsible for their key growth factors, developmental pathways and progression." (PMID 34071380, 2021). "In the literature, the increase in ZNF-281 expression is mostly correlated with gaining stem-like properties and induction of cancer progression and metastasis." (PMID 34071380, 2021). "Survival analyses from datasets of commonly occurring human cancers show that higher levels of ZNF281 correlate with poor prognosis of patients treated with DNA-damaging therapies." (PMID 31570788, 2020). "Altogether, these data suggest that ZNF281 should be evaluated as a novel marker to predict response to cancer treatments based on DNA damage induction, in line with a direct role of ZNF281 in the DDR also in pathological contexts." (PMID 31570788, 2020). "Another argument for cancer-promoting effects of ZNF281 is upregulation of its mRNA observed in primary colorectal and breast malignancies." (PMID 30885238, 2019). "Three other genes with p9 or p11 missense mutations, ZNF281, ZNF148 (ZBP89), and ZEB1, have also been identified as ZF genes important in cancer onset and progression." (PMID 29953437, 2018). "ZNF281 was highly expressed in seven cancers and correlates with the prognosis." (PMID 38880820, 2024). "We analyzed the expression and role of ZNF281 in pan-cancer." (PMID 38880820, 2024). "ZNF281 also promotes the development of multiple types of cancer." (PMID 37880213, 2023). "In most types of cancers, ZNF281 was expressed significantly higher in tumors." (PMID 36685971, 2022). "Moreover, high levels of ZNF-281 correlate with higher metastatic potential and invasiveness in several types of cancer." (PMID 36142169, 2022). "Meanwhile, in KICH and THCA, ZNF281 was downregulated in cancer." (PMID 36685971, 2022). "In this context, the activity of ZNF281 might be recognized as a potential biomarker for regeneration and cancer." (PMID 36685971, 2022). "This may be the potential reason why we observe down-regulation of ZNF-281 in OSCC when there is up-regulation in the majority of cancers." (PMID 34071380, 2021). "ZNF-281 is a zinc finger factor which can lead to cancer progression and metastasis." (PMID 34071380, 2021). "In normal oral tissues, ZNF-281 may actively participate in DNA repair, when in cancer, decreasing levels of ZNF-281 may lead to instability and carcinogenesis." (PMID 34071380, 2021). "In line with this, survival analysis of cancer patients treated with DNA damaging therapies reveals that higher expression of ZNF281 correlates with poor prognosis, suggesting that ZNF281-mediated DNA repair may favour chemoresistance." (PMID 31570788, 2020). "ZNF281 expression is increased upon DNA damage induced by drugs in several cancer types." (PMID 29152378, 2017).